BDNF (brain derived neurotrophic factor)
Diseases named in the same sentence as BDNF in open-access papers (continued):
Sharing a sentence is not in itself a finding about the gene and the disease.
depression (continued). "Brain-derived neurotrophic factor (BDNF) is considered as one of the central players in pathogenesis of major depression since altered BDNF-dependent signaling in the brain of patients is suggested." (PMID 24999483, 2014). "In recent decades, the role of BDNF in first-episode major depressive disorder MDD patients has received intensive attention." (PMID 25089150, 2014). "Low serum levels of BDNF were suggested as potential peripheral marker of depression and increase of serum BDNF as response to the appropriate first-line treatment with selective 5-HT reuptake inhibitors (SSRIs)." (PMID 25188405, 2014). "The abstracts of these articles were reviewed and those studies that reported on the interaction between life stress and BDNF Val66Met in depression were included." (PMID 24433458, 2014). "Several studies found a significant interaction between life stress and BDNF in depression using a Val recessive model." (PMID 24433458, 2014). "We found that race, depression, and platelet count were significant predictors of BDNF after simultaneous adjustment in a multivariate model." (PMID 24670553, 2014). "The assessment of BDNF appeared to demonstrate that lifestyle intervention had an effect on depression." (PMID 24524285, 2014). "In learned helplessness models of depression, a single infusion of BDNF into the dentate gyrus (DG) and CA3 pyramidal cell layers of the hippocampus show long-lasting antidepressant effects." (PMID 25628381, 2014). "Both smoking and depression alter levels of dopamine, brain-derived neurotrophic factor (BDNF) levels, and alter the activity of monoamine oxidase (MAO)." (PMID 25180682, 2014). "The downregulation of hippocampal BDNF expression has been demonstrated previously in various animal depression models and depressed patients, and the chronic treatment of almost all classes of antidepressants increases the expression of BDNF." (PMID 24523822, 2014). "Investigation concerning the intricate relationship between major factors (estrogen, glucocorticoids, cytokines, BDNF, etc.)and their specific role in the development of depression is critical." (PMID 25309465, 2014). "It is possible that at least some of the antidepressant-like effects of BDNF are mediated through BDNF-induced long-term changes in synaptic connectivity, which in turn promote recovery from depression." (PMID 24817844, 2014). "Oxidative insults, dysfunction of the HPA axis, inflammation, and reduced BDNF-related signaling have been identified as contributors to depression in obesity." (PMID 25309465, 2014). "There seemed to be a gender difference in the response of BDNF and depression to body-weight reduction." (PMID 24524285, 2014). "Previously, it was reported that intra-VTA BDNF brought about depression-like behavior, while a blockade of BDNF activity in the NAc produced antidepressant-like effects." (PMID 25628381, 2014). "It is possible that the BDNF × stress in depression is only relevant to Caucasian populations, although significant interactions have been reported among Asian and ethnically mixed populations." (PMID 24433458, 2014). "This BDNF Val66Met × 5-HTTLPR × ELS interaction in the prediction of depression was replicated in a study of adult female twins." (PMID 24596569, 2014). "As previously reported, exercise significantly induced the expression of BDNF, the mostly documented biomarker in depression, and reversed the inhibitory effects of chronic stress." (PMID 25477997, 2014). "From a broader neuropathogenic standpoint, BDNF-related signaling is blunted in several neurological disorders, specifically prominent diseases like Alzheimer, Parkinson and depression." (PMID 24804781, 2014). "In summary, while the importance of BDNF and TrkB in the antidepressant response is clear, further experiments in more refined mouse and rat models and in humans are necessary to clarify the role of BDNF signaling in depression and anxiety disorders." (PMID 24817844, 2014).
depression (continued). "The research highlighted thus far presents a case for a significant interaction between BDNF Val66Met and life stress in depression." (PMID 24433458, 2014). "BDNF levels in blacks were 1.81 ng/mL higher than whites (95% CI: 1.19, 2.43) and were 2.84 ng/mL lower in participants with depression (95% CI:−5.17, −0.51)." (PMID 24670553, 2014). "Local injection of a lentivirus coding for BDNF siRNA suggests that reduction of BDNF levels in rat HC produces depression-like behavior." (PMID 24817844, 2014). "Several lines of evidence from animal and human researches converge on the idea that BDNF is essential for hippocampal synaptic plasticity and modulation of depression." (PMID 25477997, 2014). "BDNF is reduced in elderly individuals with major depression and bipolar disorder, with distinct dynamics according to the disease stages, treatment, or the presence of cognitive impairment." (PMID 24782766, 2014). "The authors also demonstrated that the levels of BDNF and proBDNF negatively and positively correlated with major depression severity, respectively." (PMID 25089150, 2014). "The overall meta-analysis found evidence for a significant interaction between life stress and BDNF in depression using a Met dominant model." (PMID 24433458, 2014). "It has been suggested that both BDNF and glucocorticoid regulation are potential targets of therapy for major depression." (PMID 25309465, 2014). "In contrast, Nestler’s group demonstrated that BDNF in the ventral tegmental area (VTA)-nucleus accumbens (NAc) pathway is required for depression onset." (PMID 25628381, 2014). "Emotional processing biases have been associated with several depression candidate genes, such as the 5-HTTLPR polymorphism in the SLC6A4 gene, and the BDNF, COMT and NR3C2 genes." (PMID 25379724, 2014). "A subsequent study showed significantly higher levels of BDNF protein (a 40% increase) in the NAc of patients with depression, relative to controls." (PMID 25628381, 2014). "As for the mechanism of acupuncture in depression, it was reported that EA and manual acupuncture can upregulate expression of hippocampus BDNF protein and mRNA as well as its receptor TrkB." (PMID 24566146, 2014). "Decreased plasma BDNF concentrations in patients with depression and its positive correlation with cerebrospinal fluid BDNF concentration have previously been demonstrated." (PMID 24586790, 2014). "All these findings support the possibility that inflammation contributes to the development of depression by compromising neuroplasticity via reduction of BDNF." (PMID 25565964, 2014). "A study showed that heterozygous BDNF+/Met mice, carrying the human BDNF Val66Met polymorphism, exhibited decreased BDNF levels and apical dendritic spine density in the prefrontal cortex (PFC) after stress, which caused depression-like behavior." (PMID 25628381, 2014). "Other studies provided partial evidence of a significant stress × BDNF for specific types of depression, childhood adversity or detected a gender specific effect." (PMID 24433458, 2014). "A recent clinical trial demonstrated that IFN-α therapy decreased serum levels of BDNF while increasing depressive symptoms as rated by Montgomery–Asberg depression rating scale in hepatitis C patients." (PMID 25309465, 2014). "We examined the effects of these compounds on depression-like behavior, BDNF protein levels, TrkB phosphorylation, and spine density in selected brain regions, including the hippocampus, PFC, and NAc." (PMID 25628381, 2014). "In the present study, acupuncture stimulation of SP6 restored the decreased expression level of BDNF mRNA in the hippocampus and ameliorated depression- and anxiety-like behaviors in rats experiencing protracted abstinence from morphine administration." (PMID 24527041, 2014). "Gender, age, LDAEP, and psychometric ratings of patients with moderate or severe depression according to low and high BDNF levels (dichotomized at the median)." (PMID 24663244, 2014).
depression (continued). "A combination of the predefined search terms (depression + life stress + BDNF Val66Met) resulted in 1,019 hits; after duplicates were removed, 236 studies remained." (PMID 24433458, 2014). "Depressed patients were characterized by low serum BDNF levels, implying an inverse relationship between serum BDNF levels and the severity of depression." (PMID 25431319, 2014). "Depression risk as a function of child mistreatment and 5 HTTLPR status is further modified by social support and a polymorphism in the brain-derived neurotrophic factor (BDNF)." (PMID 24695633, 2014). "Studies have shown altered serum BDNF levels in a variety of neurodegenerative diseases such as AD and PD as well as in mood disorders such as depression." (PMID 24764190, 2014). "It is also possible that the BDNF-childhood adversity relationship in depression is a measurement artefact." (PMID 24433458, 2014). "It is therefore likely that LPS-induced inflammation decreased BDNF in the hippocampus and PFC but increased BDNF in the NAc, resulting in depression-like behavior in mice." (PMID 25628381, 2014). "Decreased concentrations of plasma brain-derived neurotrophic factor (BDNF) and serum BDNF have been proposed to be a state marker of depression and a biological indicator of loaded psychosocial stress." (PMID 24586790, 2014). "It is possible that more objective and sensitive approaches to measuring stressful life events are required to observe its interaction with BDNF in depression." (PMID 24433458, 2014). "The stressful events-BDNF interaction in depression was investigated in 11 studies using a combined sample of 7,594 individuals; 5 uncovered a significant effect." (PMID 24433458, 2014). "This review summarizes the studies where various mouse models with increased or decreased BDNF levels or TrkB signaling were used to evaluate the role of BDNF signaling in depression-like behavior." (PMID 24817844, 2014). "Accordingly, in this study we investigated effects of 12-week yoga intervention on pain, back flexibility, depression, and serum BDNF and serotonin levels in premenopausal women with chronic low back pain." (PMID 25120574, 2014). "Decreased plasma and serum BDNF concentrations have been observed in patients with depression and stressed subjects." (PMID 24586790, 2014). "Studies of animal models have clearly shown that BDNF plays a major role in spatial pattern separation, and that interventions known to elevated BDNF levels and ameliorate anxiety and depression enhance spatial pattern separation." (PMID 25202234, 2014). "In all, 16 studies explored the interaction between childhood adversity and BDNF in depression, 4 reported a significant effect and 5 showed partial support for this interaction." (PMID 24433458, 2014). "Our results showed that higher doses of GTS treatment (50 and 25 mg kg−1 d−1) normalized the downregulated hippocampal mRNA and protein levels of BDNF as well as decreasing the activation of CREB in the corticosterone-induced mouse depression model." (PMID 24523822, 2014). "While there is strong evidence linking BDNF to stress and depression, other neuronal growth factors are also involved, most notably glial cell-line derived neurotrophic factor (GDNF) and nerve growth factor (NGF; Hayley and Litteljohn, 2013)." (PMID 24723864, 2014). "Gender, age, BDNF levels, and psychometric ratings of patients with moderate or severe depression according to low and high LDAEP (dichotomized at the median)." (PMID 24663244, 2014). "In this review, we discuss the possible relationship between inflammation and depression, in addition to the cross-talk among cytokines, BDNF, and steroids." (PMID 25309465, 2014). "By contrast, local lentiviral knock down of BDNF in the rat dorsal DG results in anhedonic and depression-like behaviors." (PMID 24817844, 2014).
depression (continued). "When examining the specific influence of child adversity, 4 out of 16 studies reported a significant interaction with BDNF Val66Met for depression, and 5 were able to provide partial support for this interaction." (PMID 24433458, 2014). "In one study, maltreated children carrying the Met allele of BDNF Val66Met and two short alleles of 5-HTTLPR exhibit highest depression scores." (PMID 24596569, 2014). "Future studies need to recruit participants from non-Caucasian backgrounds to test the generalisability of the BDNF × stress in depression to other ethnic groups." (PMID 24433458, 2014). "Stress or chronic pain decreases the expression of BDNF in brain structures that control mood and contributes to depression." (PMID 25383981, 2014). "The rationale for the involvement of BDNF in depression comes from the observation that stress can down-regulate the expression of this neurotrophic factor in brain structures known to control emotions." (PMID 25386150, 2014). "Increasing evidence demonstrates a connection between growth factor function (including brain-derived neurotrophic factor, BDNF), glucocorticoid levels (one of the steroid hormones), and the pathophysiology of depressive disorders." (PMID 25309465, 2014). "Despite the consistence from many findings showing lower serum BDNF levels in patients with depression, decreased BDNF levels have also been found in several other disease, like Huntington’s disease, Alzheimer’s disease, schizophrenia, and bipolar disorder." (PMID 23704927, 2013). "As in the case of major depression, the mood symptoms that follow stroke have been related to impairments of BDNF." (PMID 23675319, 2013). "We posit that psychological and immune stressors can interact upon a vulnerable genetic background to promote depression by disturbing BDNF and neuroplastic processes." (PMID 24312008, 2013). "Given the complex and varied role of BDNF in the etiology of depression and antidepressant treatment more research is needed to further elucidate a mechanism through which the modulation of BDNF exerts its influence." (PMID 23691371, 2013). "Changes in peripheral concentrations of BDNF have been found in a diverse set of psychiatric diseases, including schizophrenia, depression, bipolar disorder." (PMID 25226879, 2013). "Beyond the serotonergic system, neurotrophins, especially BDNF, have been shown to promote neuronal survival, differentiation, function, and plasticity, suggesting that BDNF also plays a key role in the pathophysiology of depression." (PMID 24367510, 2013). "Brain-derived neurotrophic factor (BDNF), the most abundant neurotrophin in the brain has been linked to both anxiety and depression." (PMID 23630504, 2013). "BDNF is also thought to be involved in the pathogenesis of several neuropsychiatric disorders, and numerous studies have examined BDNF protein levels in humans, mostly in relation to depression." (PMID 23908608, 2013). "Then we further explored the roles of BDNF and its related miRNAs in patients with depression and control subjects." (PMID 23704927, 2013). "The inactivation of ERK, PKA, or CREB is capable of decreasing BDNF expression, producing depression-like phenotypes, and attenuating the actions of antidepressants." (PMID 24367510, 2013). "Recently, low serum levels of BDNF were found to be a state marker of depression that normalise during remission." (PMID 23320462, 2013). "One recent study reported intraindividual comparisons in BPD found that changes in BDNF methylation were influenced by symptoms of depression." (PMID 23951008, 2013). "Karege F. and colleagues demonstrated that cortical BDNF levels were consistent with serum BDNF levels in rodents and they also showed that serum BDNF levels were lower in patients with depression than those in matched controls." (PMID 23704927, 2013). "Summarizing briefly, the proposition that BDNF is altered in stress responses and depression has received substantial support." (PMID 23675319, 2013).
depression (continued). "Serum BDNF levels are reduced in depression, euthymic BD, acute mania, and bipolar depression and are lower with longer duration of illness." (PMID 25505691, 2013). "The expressions of glial cell-derived neurotrophic factor (GDNF) and brain-derived neurotrophic factor (BDNF) are also regulated by stress-related mood disorder and depression." (PMID 23878590, 2013). "In a previous sub-analysis of the PREDIMED trial, conducted by our group in the PREDIMED-NAVARRA center, significantly higher plasma BDNF levels were seen for patients with depression assigned to the MD-nuts compared with those assigned to a control diet." (PMID 24229349, 2013). "Our results clearly indicate that BDNF and its related miRNAs play important roles in the pathogenesis of depression." (PMID 23704927, 2013). "Predictably, given stressor involvement in depression, BDNF is affected by recent stressors as well as stressors such as neglect experienced in early life." (PMID 23824678, 2013). "In line with a role for BDNF in depression, low serum BDNF levels were accompanied by a poorer treatment response than among those depressed individuals with higher BDNF levels." (PMID 23824678, 2013). "Our results showed that the serum BDNF levels in patients with depression were significantly decreased compared with controls." (PMID 23704927, 2013). "After adjustment for age, gender, BMI and HbA1c, BDNF Val/Met genotypes were still independently correlated with depression scores (OR = 1.952, p < 0.05)." (PMID 23968401, 2013). "A growing number of clinical and experimental studies have demonstrated that depression is accompanied by decreased levels of BDNF and serotonin." (PMID 24367510, 2013). "Next, we measured the serum levels of BDNF, miR-132 and miR-182 in human subjects with depression and controls." (PMID 23704927, 2013). "Our results show that, for Chinese subjects, there is a positive association between BDNF Val66Met polymorphism and comorbid depression in T2DM patients and Met allele carriers are susceptible to suffer from depression." (PMID 23968401, 2013). "Based on depression models, BDNF has been shown to exhibit a pronouncedantidepressant effect upon central administration." (PMID 24455189, 2013). "The case for BDNF involvement in depression has generally been impressive but as discussed, the available data do not fully conform to an accounting based solely on BDNF-mediated neurogenesis or neuroplasticity." (PMID 23675319, 2013). "Anhedonia, brain BDNF and circulating corticosterone levels, considered endophenotypes of depression, were investigated." (PMID 23653679, 2013). "Clinical studieshave shown that the BDNF blood content in patients with severe depression issignificantly reduced and recovers after the administration of antidepressants." (PMID 24455189, 2013). "In current study, we characterized the roles of BDNF and its related miRNAs in the pathogenesis of depression." (PMID 23704927, 2013). "In the present study, we investigated the 5-HT2A T102C, 5-HT2A A-1438G, BDNF Val66Met and 5-HT1A C-1019G gene polymorphisms in depression patients with two type of abnormal humor in TUM." (PMID 24274373, 2013). "BDNF initiates TrkB receptor-dependent different intracellular signaling pathway and exhibits beneficial effect for the treatment of depression in experimental studies." (PMID 23573124, 2013). "Collectively, HD shares certain hallmarks with a large portion of clinical depression patients: namely, disturbances of the 5-HT system, BDNF expression, and HPA-axis dysregulation." (PMID 23847583, 2013). "Several studies have shown down-regulation of BDNF in the hippocampus after exposure of animals to various types of stress, and in postmortem studies of suicide-depression patients." (PMID 23422934, 2013). "Individuals with type 2 diabetes (T2DM) have a high prevalence of major depression and low levels of BDNF." (PMID 23968401, 2013).